GRB14 (growth factor receptor bound protein 14)
Diseases named in the same sentence as GRB14 in open-access papers (continued):
Sharing a sentence is not in itself a finding about the gene and the disease.
Tourette syndrome (1 paper, 2018). A neurologic disorder caused by defective metabolism of the neurotransmitters in the brain. "We discuss the association of SCN2A, SCN3A, GRB14, COBLL1 and SCL38A11 deletions with ASD and Tourette syndrome and possible implications for treatment." (PMID 30071822, 2018).
tumor (5 papers, 2015 to 2025). "Growth factor receptor-bound protein 14 (GRB14) is crucial in cell signal transduction and is associated with tumor growth, invasion, and metastasis." (PMID 40321159, 2025). "GRB14 has been linked with several cancer types, with evidence that it promotes tumour progression in thyroid carcinoma and glioblastoma, and may act as a tumour suppressor in hepatocellular carcinoma." (PMID 39343875, 2024). "The mechanism that GRB14 promoted tumor progression may be related to the downstream signal transduction pathway PDGFR." (PMID 33867829, 2021). "Similar to Grb10, Grb2, Grb7 and Grb14 expression varied among different control organs examined, however none were overexpressed in any tumor cell line compared to control tissues, arguing against compensatory overexpression of Grb family members in response to reduced Grb10 expression." (PMID 26000738, 2015).
cancer (4 papers, 2017 to 2024). A tumor composed of atypical neoplastic, often pleomorphic cells that invade other tissues. "Depletion of Grb14 from parental cancer cells increased proliferation by only 1.04–1.12 fold whereas Grb14 depletion from the IMP2-deficient variants increased their proliferation by 1.5–2.09 fold." (PMID 28753127, 2017). "As in MEFs, deletion of IMP2 from the cancer cell lines is accompanied by a marked increase in the abundance of Grb14 and IGFBP2, and overexpression of IMP2 reduces the abundance of both the IGFBP2 and Grb14 polypeptides." (PMID 28753127, 2017). "However, the expression level, role, and prognostic value of GRB14 in malignant tumors had often been controversial 34-37." (PMID 33867829, 2021). "We conclude that the pro-proliferative effect of IMP2 in most cancer derived cell lines is mediated predominantly by upregulation of IGF2 production and suppression of Grb14 and IGFBP2 polypeptide abundance which together facilitate IGF2 signaling." (PMID 28753127, 2017).
metabolic disease (4 papers, 2018 to 2024). A congenital disorder (due to inherited enzyme abnormality) or acquired (due to failure of a metabolically important organ) disorder resulting from an abnormal metabolic process. "GRB14 has been consistently linked to ‘metabolic disease’ and is negatively correlated (R = –0.36) with IS in the present and other published analyses." (PMID 29986096, 2018). "Therefore, sex-specific effects need to be carefully considered in further studies aimed at clarifying the role of COBLL1 and GRB14 in adverse body FD and associated metabolic disorders." (PMID 35955692, 2022). "We independently identified many known IS regulators, including GRB14, a receptor tyrosine kinase adaptor protein which inhibits insulin signaling, located at a GWAS significant metabolic disease loci, while providing the first detailed map of the relationship between lncRNAs and IS." (PMID 29986096, 2018). "Considering the strong correlation of GRB14/COBLL1 mRNA expression in AT and its potential function on lipid metabolism, we may need to consider the interaction of COBLL1 and GRB14 in adverse body FD and associated metabolic disorders in further studies." (PMID 35955692, 2022). "GRB14/COBLL1 locus has been shown to be associated with body fat distribution (FD), but neither the causal gene nor its role in metabolic diseases has been elucidated." (PMID 35955692, 2022).
GRB14 also shares sentences with these, for which no sentence is quoted: hepatocellular carcinoma (2 papers); Hypertension (2); Alzheimer disease (1); Impaired glucose tolerance (1); lipodystrophy (1).